ATM (ATM serine/threonine kinase)
Diseases named in the same sentence as ATM in open-access papers (continued):
Sharing a sentence is not in itself a finding about the gene and the disease.
acute leukemia (6 papers, 2015 to 2025). A clonal (malignant) hematopoietic disorder with an acute onset, affecting the bone marrow and the peripheral blood. "Particular mutations such as ataxia telangiectasia mutated (ATM) gene are associated with the defects in DNA repair mechanisms and are present in various cancers including acute leukemia." (PMID 33036137, 2020). "We have previously shown that CX-5461 activates ATM/ATR pathway in acute leukemia, arrests cells in G2 phase and synergizes with ATR inhibitor in killing these cells." (PMID 26472108, 2015). "Testing of ATM inhibitors in acute leukemia is so far largely confined to preclinical investigations but early-phase clinical trials in other cancers have been completed or initiated (e.g., NCT03423628, NCT05116254, NCT05182905, NCT05396833, NCT06433219, NCT06894979)." (PMID 41514580, 2025). "Our observation that inhibition of ATM or MDM2 sensitizes acute leukemia cells to CLM may provide the rationale for the clinical exploration of a combination therapy with either GO or InO." (PMID 41514580, 2025). "Therefore, PN could be developed as a drug for acute leukemia; in addition, miR-181b-5p and ATM may be promising therapeutic targets." (PMID 37208425, 2023).
autoimmune disease (6 papers, 2021 to 2023). A disorder resulting from loss of function or tissue destruction of an organ or multiple organs, arising from humoral or cellular immune responses of the individual to their own tissue constituents. "Most genes were related to autoimmune diseases like ATM, NCF1, MCM4, FCN3, and DOCK8 or autoinflammatory diseases associated with the release of IFN-gamma, such as PRF1, NOD2, and MEF." (PMID 37588055, 2023). "Some organ-specific autoimmune disorders were observed in these patients including hematologic autoimmunity in patients with PNP, STIM1, ORAI1, WAS, ATM, and STAT5B mutations or early-onset inflammatory bowel disease in patients with WAS, DNMT3B, and ZBTB24 mutations." (PMID 36544766, 2022).
Burkitt lymphoma (6 papers, 2015 to 2021). A rare form of malignant mature B-cell non-Hodgkin lymphoma. "In assays with an ATM inhibitor and DNA damaging reagents in Burkitt lymphoma cell lines, γH2AX induction was necessary for optimal expression of early EBV genes, but not sufficient for lytic reactivation." (PMID 25950714, 2015).
COVID-19 (6 papers, 2021 to 2023). A disease caused by infection with severe acute respiratory syndrome coronavirus 2. "We nevertheless cannot exclude the possibility that the ATM deficiency modified the course of COVID-19 in our TLR7-deficient patient." (PMID 34686943, 2022). "It is unknown if the antibody and T cell defects associated with the ATM deficiency may contribute to severe COVID-19." (PMID 34686943, 2022). "Herein, we present the detailed clinical, immunological and genetic characterization of a unique IEI patient with critical COVID-19 pneumonia, who has pathogenic mutations in both X-linked TLR7 and autosomal ATM (reported as P6 in a large COVID-19 cohort, with a TLR7 mutation)." (PMID 34686943, 2022). "The potential that the ATM deficit influenced the progression of COVID-19 in the TLR7-deficient case cannot be ruled out." (PMID 37521843, 2022). "Several studies have shown that DNA damage due to ATM deficiency primes the type I IFN system via the cytosolic DNA sensor STING, which might provide robust antimicrobial responses and protect A-T patients from severe COVID-19." (PMID 34686943, 2022). "Indeed, ATM is known to regulate these pathways in COVID-19, as shown in previous study." (PMID 35434729, 2022). "However, as our other SARS-CoV-2 infected A-T patients, including those with a HIgM phenotype, did not have severe COVID-19, the ATM mutation identified here is probably underlying the primary antibody deficiency (HIgM) in this patient, but not the critical COVID-19." (PMID 34686943, 2022).
mesothelioma (6 papers, 2021 to 2025). A usually malignant and aggressive neoplasm of the mesothelium which is often associated with exposure to asbestos. "Our extensive testing in preclinical models of BAP1-deficient mesothelioma show that inhibiting ATM in combination with EZH2 is highly synergistic, showing the potential therapeutic application of this combination." (PMID 38519707, 2024). "In summary, we demonstrate that the simultaneous inhibition of EZH2 and ATM is a highly synergistic regimen against preclinical models of BAP1-deficient mesothelioma." (PMID 38519707, 2024). "To get more insight in the potential link between BAP1 loss and reduction in ATM levels, we performed RNA sequencing on the mesothelioma cell lines with an inducible shBAP1 construct and compared these lines to cells transduced with an inducible shRANDOM construct." (PMID 38519707, 2024). "In line with that hypothesis, in the current study we show that the acute loss of BAP1 in mesothelioma cells leads to the subsequent loss of ATM expression at both mRNA and protein level." (PMID 38519707, 2024). "We demonstrated the efficacy of the combination of ATM and EZH2 inhibition against BAP1-deficient mesothelioma in preclinical models, indicating the potential of this combination as a novel treatment modality using BAP1 as a biomarker." (PMID 38519707, 2024). "Our results thus not only revealed lots of potential candidates for ATM but also unveiled a mechanism that a new ATM substrate UBQLN4 regulates apoptosis in mesothelioma by stabilizing BCL2A1 and BCL2L10." (PMID 34245648, 2021). "Interestingly, we see that the included ATM inhibitor AZD1390, shows high synergistic scores in Bap1-deficient mouse mesothelioma cell lines and in human cell lines almost exclusively in BAP1-deficient cells." (PMID 38519707, 2024). "Taken together, our data suggest that ATM‐mediated phosphorylation of UBQLN4 at Ser318 may regulate mesothelioma cell apoptosis in response to DNA damage." (PMID 34245648, 2021). "We found UBQLN4 as a new ATM substrate, which was upregulated in mesothelioma." (PMID 34245648, 2021). "Taken together, all this data warrants further research into the indirect link between BAP1 and ATM and how this might affect DSB repair, and facilitates the investigation for clinical possibilities of this combination strategy against BAP1-deficient mesothelioma." (PMID 38519707, 2024). "Taken together, we uncover that about fifty potential substrates for ATM and clarify the mechanism that UBQLN4 inhibits the apoptosis in mesothelioma by phosphorylating the site of Ser318 and stabilizing BCL2A1 and BCL2L10." (PMID 34245648, 2021). "We determined dose–response curves of ATM inhibition for the tested human mesothelioma cell lines showing that there is no clear difference in sensitivity between Bap1-deficient and proficient cell lines for ATM inhibition only." (PMID 38519707, 2024). "In this study, we not only identified UBQLN4 as a substrate for ATM, but also found that UBQLN4 interacts with and stabilizes the anti‐apoptotic proteins Bcl‐2‐related protein A1 (BCL2A1) and Bcl‐2‐like protein 10 (BCL2L10) and prevents mesothelioma cell apoptosis in response to DNA damage." (PMID 34245648, 2021). "AtM B cells exhibit an exhausted phenotype and are increased in non-small cell lung cancer (NSCLC) and mesothelioma patients with non-response to ICB therapy, suggesting that AtM B cells may impede the ICB treatment response." (PMID 39744696, 2025).
microcephaly (6 papers, 2013 to 2023). A congenital or acquired developmental disorder in which the circumference of the head is smaller than normal for the person's age and sex. "Nucleotide excision repair proteins, ataxia telangiectasia mutated (ATM) and Fanconi anaemia pathway proteins, which are associated with neurodegeneration, neurodevelopmental defects or microcephaly, have recently been implicated in RNA:DNA-hybrid resolution." (PMID 30345028, 2018). "Loss of ATR is embryonic lethal and hypomorphic mutations mimicking those found in human Seckel syndrome result in severe microcephaly in mice and are synthetically lethal with ATM deficiency." (PMID 23532176, 2013).
myeloid malignancies (6 papers, 2020 to 2025). "P/LP likely germline variants in genes that have previously been associated with adult myeloid malignancy were found in 16 patients (4.4%), including ATM, BRCA2, CHEK2, and TNFRSF13B." (PMID 40766138, 2025). "Germline LOF mutations in the ATM gene have long been associated with early-onset myeloid malignancies, in addition to solid tumors such as breast and pancreatic cancers." (PMID 38203823, 2024). "In contrast to myeloid malignancies, germline ATM variants, either in the heterozygous state or in the context of true A-T with biallelic ATM variants, have been strongly associated with the development of lymphoid malignancies." (PMID 38203823, 2024).
oral cancer (6 papers, 2019 to 2025). "In oral cancer, high expressions of ISG15, IFI27, and OASL were found to be associated with low ATM expression (mimicry of ATM inhibition), the activation of inflamed immune pathways, and elevated tumor-infiltrated scores of pDC, NK, and CD8+ T cells." (PMID 37174688, 2023). "Among these ISGs, the high expressions of ISG15, IFI27, and OASL were associated with low ATM expression, the activation of immune pathways, and high tumor-infiltrating scores of DCs, NK, and cytotoxic CD8+ T cells in oral cancer." (PMID 37174688, 2023). "In oral cancer, high expressions of ISG15, IFI27, and OASL were associated with low expressions of ATM, the activation of inflamed immune pathways, and increased tumor-infiltrating scores of CD8+ T, natural killer, and dendritic cells." (PMID 37174688, 2023). "Although ATM inhibition-elicited interferon response is demonstrated in some cancer cells, it is unclear whether this immune activation can be found in oral cancer or cisplatin-resistant (CDDP-R) cancers." (PMID 37174688, 2023).
pancreatic adenocarcinoma (6 papers, 2018 to 2023). "In apparently sporadic pancreatic adenocarcinoma patients, ATM germline PVs were identified in 1.2% of pancreatic adenocarcinoma patients." (PMID 35008949, 2022). "Canonical pathways for ‘GADD45 Signaling’, ‘ATM Signaling’, ‘Pancreatic Adenocarcinoma Signaling’, ‘ATM Signaling’, ‘14-3-3-mediated Signaling’ and UVA-Induced MAPK Signaling’ were significantly affected in four out of the five conditions investigated." (PMID 29177809, 2018).
rheumatoid arthritis (6 papers, 2012 to 2024). A chronic, systemic autoimmune disorder characterized by inflammation in the synovial membranes and articular surfaces. "An ATM deficiency has been described in CD4+ T cells from rheumatoid arthritis (RA) patients, associated with premature immunosenescence." (PMID 23092393, 2012). "An additional link between the PPP and ATM stems from observations in rheumatoid arthritis patients, who display deranged DNA repair in T-cells." (PMID 31653834, 2019). "In rheumatoid arthritis T cells, reduced ATM was identified at baseline." (PMID 34009545, 2021).
thymoma (6 papers, 2017 to 2024). A neoplasm arising from the epithelial cells of the thymus. "Generally, a third of mice with ATM deficiency died from complications related to large thymic cancers (thymoma) found in the thoracic cavity." (PMID 34723800, 2021). "(C) Pie charts illustrating that ATM-deficient mice displayed a high prevalence of thymomas based on postmortem necropsies." (PMID 34723800, 2021). "Few literature observations, mainly BRCA1/2 and ATM, are available about single case or families with sporadic/recurrent thymomas." (PMID 39273507, 2024). "We also identified previous unknown associations such as a second hit in ATM of a patient with bile duct cancer and a second hit in BLM in a patient with thymoma." (PMID 31263571, 2019).
urothelial carcinoma (6 papers, 2015 to 2024). A malignant neoplasm derived from the transitional epithelium of the urinary tract (urinary bladder, ureter, urethra, or renal pelvis). "The ATM gene is altered in ~6% of all human cancers and in ~11% of human urothelial carcinomas, and showed missense mutations in three samples in the present study, all of which were UDV595E specimens." (PMID 37079639, 2023). "Based on these concerns, future studies evaluating ATR inhibitors may focus on pre-selecting by ATM mutational status given its prevalence in urothelial carcinoma to identify those most likely to benefit from therapy." (PMID 36604210, 2023).
uterine cancer (6 papers, 2017 to 2023). Primary or metastatic malignant neoplasm involving the uterine corpus and/or the cervix. "ATM, BRCA, CHECK2, and CDK12 mutations were frequent in cholangiocarcinoma (N = 34) with similar results in uterine carcinoma (N = 57), though the significance of these results is limited by small sample sizes." (PMID 33214570, 2020).
anemia (5 papers, 2009 to 2025). A reduction in the number of red blood cells, the amount of hemoglobin, and/or the volume of packed red blood cells. "CDK12 is involved in the DNA-damage repair (DDR) pathway by regulating the expression of several DDR machinery components, including BRCA1, ATM, ATR, and Fanconi anemia (FANC) genes." (PMID 40148269, 2025). "BRCA1 and 2 interacts with a number of other DNA repair proteins to form a complex system for DNA damage repair, including ATM, RAD51, PALB2, MRE11A, RAD50, NBN, and the Fanconi anemia proteins." (PMID 35785170, 2022).
autism (5 papers, 2021 to 2025). Persistent deficits in social interaction and communication and interaction as well as a markedly restricted repertoire of activity and interest as well as repetitive patterns of behavior. "Also, in a Taiwanese Han population, a specific runs of homozygosity region associated with the language impairments of autism has been found on 11q22.3 chromosome, a region that contains the ATM gene." (PMID 33373327, 2021). "Enhanced ATM levels have been observed in two autism models, Rett syndrome and prenatal VPA exposure, exhibiting delayed GABAergic switch." (PMID 40520207, 2025). "We exploited 2 different animal models of autism, the methyl CpG binding protein 2–null (Mecp2y/–) mouse model of Rett syndrome and mice prenatally exposed to valproic acid, and found increased ATM levels." (PMID 33373327, 2021). "Here, we show for the first time to our knowledge how the abnormal expression of ATM affects the pathological condition of autism." (PMID 33373327, 2021). "ATM expression is higher in hippocampal tissues of 2 animal models of autism." (PMID 33373327, 2021). "In order to unveil the possible involvement of ATM in ASD, we took advantage of 2 different animal models, Mecp2y/– mice and mice prenatally exposed to valproic acid (VPA), as genetically and pharmacologically linked models of autism." (PMID 33373327, 2021). "Further experiments are needed to better investigate the involvement of ATM in other neurological states, such as autism and epilepsy, since these pathologies may result from insufficient KCC2 levels and hyperexcitability." (PMID 33373327, 2021). "Our data indicate that among the pathological modifications that occurred in the mouse models of autism such as in Mecp2y/– mice and in the VPA model, a higher ATM activity contributed to the generation of the altered neuronal phenotype." (PMID 33373327, 2021). "Treatment with KU55933, an ATM inhibitor, was able to restore normal levels of KCC2, rescuing abnormal GABAergic signaling and autism-like behavior in mice." (PMID 34439564, 2021). "Interestingly, inhibition of ATM can reinstate the expression of KCC2, which rescues abnormal GABAergic signaling, as well as autism-like behaviors, in mice." (PMID 40520207, 2025). "Finally, we moved to in vivo experiments to evaluate KU effects in the VPA mouse model of autism, since these mice display a delayed GABA switch, a long-lasting excitatory action of GABA, and higher ATM levels." (PMID 33373327, 2021). "To further demonstrate that acute ATM inhibition in adults is not responsible for KARs increments, we challenged the valproic acid (VPA) mouse model for autism spectrum disorder, a model of autism where we described increased ATM expression." (PMID 35842432, 2022).